EPHA7 (EPH receptor A7)
Diseases named in the same sentence as EPHA7 in open-access papers (continued):
Sharing a sentence is not in itself a finding about the gene and the disease.
follicular lymphoma (6 papers, 2015 to 2016). Follicular lymphoma is a form of non-Hodgkin lymphoma characterized by a proliferation of B cells whose nodular structure of follicular architecture is preserved. "This is also supported by recent studies that showed inhibition of invasion and tumor growth by EPHA7 in follicular lymphoma and by EPHA4 in lung adenocarcinoma." (PMID 27095580, 2016). "On the other hand, EPHA7 has been identified as a soluble tumor suppressor for follicular lymphoma." (PMID 27058903, 2016). "Taken together, our results support the idea that silencing of EPHA7 in human follicular lymphoma and medulloblastoma might occur upon BMI1 overexpression." (PMID 27533460, 2016). "One study showed a tumor-suppressor role of EPHA7 in follicular lymphoma." (PMID 27195705, 2016). "Furthermore, a truncated form of EPHA7 has been reported to act as a tumor suppressor in follicular lymphoma, and it would thus be interesting to study its potential role in lung tumor suppression in conjunction with EphA3 loss of function." (PMID 25713296, 2015). "The truncated form of EPHA7 (EPHA7TR) was revealed as a soluble tumor suppressor for follicular lymphoma by inhibiting EPHA2 signaling, which makes EPHA7 a promising targeted therapeutic polypeptide." (PMID 27681722, 2016). "EPHA7 expression is low to absent in a large fraction of certain human hematological malignancies: germinal center B-cell Non-Hodgkin lymphomas, follicular lymphomas, and T cell lymphomas." (PMID 27533460, 2016).
melanoma (6 papers, 2010 to 2023). A malignant, usually aggressive tumor composed of atypical, neoplastic melanocytes. "Secondly, mutation rate of EPHA7 in melanoma was nearly 2.5 times higher than in other cancer types." (PMID 33526018, 2021). "The overall mutation frequency of EPHA7 was 2.7% (287/10,437) in TCGA pan-cancer cohort with melanoma (13.6%) ranking first followed by non-small cell lung cancer (5.6%) and endometrial carcinoma (5.6%)." (PMID 33526018, 2021). "Deletion of EPHA4 and EPHA7 loci in thick melanomas is consistent with decreased expression of EPHA4 and EPHA7 mRNA in metastatic compared to primary melanomas." (PMID 27095580, 2016). "Three neuronal-related genes (PCLO, PLXNA4, and EPHA7), and the gene encoding the leptin receptor (LEPR), all reported as mutated in melanoma at a variable frequency (37%, 11%, 16% and 8% of samples in TCGA cohort, respectively), were altered more frequently in R compared to NR patients." (PMID 37739939, 2023). "Deletion of EPHA4 and EPHA7 loci, that we found in two out of five thick melanomas, correlates with their reduced expression in metastatic compared to primary melanomas, suggesting that EPHA4 and EPHA7 might act as tumor suppressor during melanoma progression." (PMID 27095580, 2016).
cervical carcinoma (5 papers, 2020 to 2025). A carcinoma arising from either the exocervical squamous epithelium or the endocervical glandular epithelium. "We performed an integration study to identify and validate the association between EphA7 methylation and cervical cancer." (PMID 35681118, 2022). "dCas9-TET1CD was used to demethylate the EphA7 gene: the protein correlates with life expectancy in cervical cancer, indicating the potential of dCas9-TET1CD as a therapeutic strategy for cervical cancer." (PMID 37239005, 2023). "EphA7 hypermethylation is present in cervical cancer and is a potential biomarker for the diagnosis of cervical cancer." (PMID 35681118, 2022). "Pooled analysis showed that EphA7 promoter methylation levels were significantly increased in cervical cancer compared to normal tissues (P < 0.001) and negatively correlated with EphA7 expression." (PMID 35681118, 2022). "First, data on EphA7 methylation and expression in cervical cancer were extracted and analyzed via bioinformatics tools." (PMID 35681118, 2022). "Ultimately, the clinical value of EphA7 methylation in cervical cancer was validated in cervical tissues and Thinprep cytologic test (TCT) samples by methylation-specific PCR (MSP) and quantitative methylation-specific PCR (QMSP), respectively." (PMID 35681118, 2022). "EphA7 was notably hypermethylated and downregulated in cervical cancer compared with normal tissues (P < 0.05)." (PMID 35681118, 2022). "Aberrant methylation of the EphA7 promoter has been observed in cervical cancer (CC); however, its precise function and role in CC remain largely unknown." (PMID 40258813, 2025).
glioma (5 papers, 2008 to 2024). A benign or malignant brain and spinal cord tumor that arises from glial cells (astrocytes, oligodendrocytes, ependymal cells). "Some members, such as EPHA2 and EPHA7, are overexpressed in glioma stem cells, indicating a poor prognosis." (PMID 38612645, 2024). "A poor prognosis has been documented for pediatric patients with gliomas overexpressing EPHA7, alveolar-type rhabdomyosarcomas overexpressing EPHB4, and osteosarcomas presenting ephrin-A4 cytoplasmic expression." (PMID 38612645, 2024). "For instance, when “receptor” and “glioma” were selected, we found datapoint EPHA7 (Ephrin type-A receptor-7) not overexpressed in the gene-level, but was in close proximity of several receptors all associated with the cancer." (PMID 37743473, 2023).
leukemia (5 papers, 2008 to 2025). A malignant (clonal) hematologic disorder, involving hematopoietic stem cells and characterized by the presence of primitive or atypical myeloid or lymphoid cells in the bone marrow and the blood. "For example, the N-terminal extracellular fragment of EphA7, acting as an agonist, induced apoptosis in leukemia cells in xenotransplanted mice." (PMID 33007931, 2020). "It should be noted that a prior study found EPHA7 to be methylated in several leukemia cell lines and acute lymphoblastic leukemia patient samples, which may be dependent on various experimental conditions." (PMID 41020821, 2025). "A possible explanation for lack of effect of EphA2 deletion in MLL-AF9 leukemia is that other Eph proteins with overlapping ephrin-binding affinities, such as EphA7 that was reported previously on MLL-AF9 leukemias, might show a compensatory increase in expression." (PMID 26083390, 2015). "A recent study on signaling pathways involved in EphA7 RTK reported that direct EphA7 knockdown can result in attenuation of ERK1/2 phosphorylation and induce apoptosis of leukemia cells, suggesting the impact of EphA7 on the growth of tumor cells." (PMID 18366728, 2008). "Like CD34‐positive leukemia‐initiating AML cells we find ROBO4 significantly overexpressed in CD34‐positive ALL samples, but we also find other axonal growth guidance genes upregulated, such as EFNB1 and EPHA7." (PMID 35271751, 2022).
lymphoma (5 papers, 2012 to 2025). A malignant (clonal) proliferation of B- lymphocytes or T- lymphocytes which involves the lymph nodes, bone marrow and/or extranodal sites. "Another report supported that EPHA7 might be a new tumor suppressor gene for 6q deletions in T-cell lymphoblastic leukemia/lymphoma." (PMID 33439936, 2021). "EphA7 silencing has been reported in several different human tumor types including lymphomas, and our data suggest BMI1 overexpression as a novel mechanism leading to EphA7 inactivation via H3K27 trimethylation and DNA methylation." (PMID 27533460, 2016).
non-small cell lung carcinoma (5 papers, 2016 to 2022). A group of at least three distinct histological types of lung cancer, including non-small cell squamous cell carcinoma, adenocarcinoma, and large cell carcinoma. "EPHA7 has been reported in several cancers, such as non-small cell lung cancer, human laryngeal cancer, and adenocarcinoma." (PMID 33439936, 2021). "EPHA7 may also be sequestering a microRNA, namely miR-944, which, when expressed at a high level, has been shown to facilitate proliferation of non-small cell lung cancer cells." (PMID 30962767, 2019).
hepatocellular carcinoma (4 papers, 2008 to 2022). A malignant tumor that arises from hepatocytes. "The increased expression of EPHA7 was observed in different cancers, among others in hepatocellular carcinoma, and was associated with tumor progression, invasion, and metastasis." (PMID 35628654, 2022). "Upregulation of EPHA7 was observed in many cancers, including hepatocellular carcinoma, where it was associated with tumor progression, invasiveness, and metastasis." (PMID 32283808, 2020). "In hepatocellular carcinoma, a high level of expression of EPHA7 protein may play an important role in malignant transformation and tumour progression, invasion and metastasis." (PMID 28611294, 2017).
medulloblastoma (4 papers, 2015 to 2025). A malignant, invasive embryonal neoplasm arising from the cerebellum. "In the present study, we investigated the effects of genetic loss of ephrin-A5, EphA4, and EphA7 on the spatiotemporal development of medulloblastoma tumors in the context of the smoothened transgenic mouse model system." (PMID 26345456, 2015). "EphA7 expression is markedly reduced in medulloblastoma cell lines relative to normal tissue, indicating a distinct role in tumor biology." (PMID 41200151, 2025). "Genetic alteration of EphA4/EphA7 yields no consistent effect on tumor size in the Smo/Smo mouse medulloblastoma model." (PMID 26345456, 2015).
osteosarcoma (4 papers, 2020 to 2024). A usually aggressive malignant bone-forming mesenchymal neoplasm, predominantly affecting adolescents and young adults. "Mostly, the upregulation of EPH receptors leads to tumor-promoting functions in bone sarcomas such as tumor cells migration and proliferation by EPHA2, along with enhanced carcinogenesis and invasion by EPHA7 in osteosarcoma." (PMID 35563562, 2022). "Additionally, EPHA7 regulation by microRNAs (miRs) has been shown to be involved in osteosarcoma pathogenesis, with EPHA7 exerting a tumor-promoting role." (PMID 38612645, 2024). "Therefore, the HCP5/miR-101/EPHA7 axis has been correlated to osteosarcoma malignant development, as HCP5 promotes the increased expression of EPHA7 via targeting miR-101 competitively." (PMID 35563562, 2022). "Consequently, HCP5, miR-101 and EPHA7 could be further considered as potential prognostic biomarkers and therapeutic targets for osteosarcoma treatment." (PMID 35563562, 2022). "Similarly, Wu et al31 showed that elevated expression of miR‐448 suppressed osteosarcoma cell proliferation and invasion through targeting EPHA7, indicating that circMATR3 may reverse the inhibitory roles by absorbing miR‐448." (PMID 32166857, 2020).
prostate tumor (4 papers, 2017 to 2025). "As an upstream factor, EphA7 interferes with PTEN/PI3K/AKT signaling to regulate cell apoptosis in prostate tumors and laryngeal squamous cell carcinoma; however, little information on the role of EphA7 in CC has been obtained to date." (PMID 40258813, 2025). "However, the detailed mechanism of EphA7-mediated prostate tumor progression remains elusive." (PMID 29022918, 2017). "Another study in prostate tumor growth and progression demonstrated that ligand-dependent EphA7 containing tyrosine site induced prostate tumor cell apoptosis, but the truncated secreted form EphA7 did not have this effect." (PMID 31685980, 2020).
autism (3 papers, 2013 to 2020). Persistent deficits in social interaction and communication and interaction as well as a markedly restricted repertoire of activity and interest as well as repetitive patterns of behavior. "Some of the genes, such as NCAN and EPHA7, have similar functionality as NRXN1 in mediating neuronal cell interactions, while some other genes, such as PCDH19, CNTN3, CTNNA3, LMX1B, are known autism candidate genes." (PMID 23536886, 2013).
esophageal squamous cell carcinoma (3 papers, 2020 to 2022). Esophageal squamous cell carcinoma (ESCC) is a type of esophageal carcinoma (EC) that can affect any part of the esophagus, but is usually located in the upper or middle third. "In esophageal squamous cell carcinoma, low expression of EphA7 results in more frequent lymph node metastases, poorer tumor differentiation, and a higher grade in TNM classification." (PMID 33007931, 2020). "Regulation of EPHA7 by miR-196b was also observed in esophageal squamous cell carcinoma." (PMID 35008952, 2022).
gallbladder adenocarcinoma (3 papers, 2014 to 2022). A carcinoma that arises from glandular epithelial cells of the gall bladder. "In gallbladder adenocarcinoma, the expression level of EPHA7 was an independent poor-prognostic predictor, and the elevated expression of EPHA7 was closely related to carcinogenesis, disease progression and a poor prognosis." (PMID 28611294, 2017). "In gallbladder adenocarcinoma, the positive expression of EphA7 and AEG-1/MTDH has been found to significantly correlate with differentiation, tumor masses, lymph node metastasis, invasion and OS, and is an independent poor prognostic predictor, as determined by multivariate analysis." (PMID 25009642, 2014). "The elevated expression of EphA7 and/or AEG-1/MTDH has also been found to closely correlate with the carcinogenesis, progression, clinical biological behavior and prognosis of gallbladder adenocarcinoma." (PMID 25009642, 2014). "The immunohistochemical analysis of 96 benign and 108 malignant lesions of the gallbladder revealed that the positive expression of erythropoietin-producing hepatoma-amplified sequence receptor A7 (EphA7) and AEG-1/MTDH is significantly higher in gallbladder adenocarcinoma than in benign lesions." (PMID 25009642, 2014).
laryngeal carcinoma (3 papers, 2016 to 2021). Carcinoma that arises from the laryngeal epithelium. "Depletion of EphA7 has remarkably inhibited the proliferation and invasion in human laryngeal cancer cell lines." (PMID 27058903, 2016).
laryngeal squamous cell carcinoma (3 papers, 2019 to 2025). A squamous cell carcinoma that arises from the larynx. "For instance, EPHA7 was up-regulated in human laryngeal squamous cell carcinoma tissues, and EPHA7 suppression inhibited cell growth and promoted cell apoptosis." (PMID 33439936, 2021). "In laryngeal squamous cell carcinoma, upregulated EphA7 was observed in human laryngeal squamous cell carcinoma samples, while down-regulation of EphA7 effectively suppressed cell growth and promoted cell apoptosis." (PMID 31540331, 2019).
lung adenocarcinoma (3 papers, 2014 to 2022). A carcinoma that arises from the lung and is characterized by the presence of malignant glandular epithelial cells. "Several mutations in Eph family members, including EphA3, A5, A7, B1 and B6 were identified in lung adenocarcinoma, while advanced stage tumours presented accumulated more EphA7 mutations compared to low stage tumours." (PMID 24495444, 2014). "Moreover, knockdown of EphA7 in lung adenocarcinoma has been found to increase apoptosis through regulation of BAX, Bcl-2, and caspase-3." (PMID 35103233, 2022).
lymph node metastasis (3 papers, 2021 to 2022). "Our study also linked high EPHA4 expression with the presence of lymph node metastasis and high EPHA7 expression with a higher nuclear grade of tumor cells, both at no significant level though." (PMID 35204461, 2022).
pancreatic cancer (3 papers, 2020 to 2022). "EPHA7 mutation may serve as a prognostic biomarker to predict the treatment efficacy of AG chemotherapy in locally advanced pancreatic cancer." (PMID 35664782, 2022). "Particularly, KRAS and EPHA7 are highly likely to serve as prognostic factors and therapeutic targets in the management of locally advanced pancreatic cancer." (PMID 35664782, 2022).
developmental delay (2 papers, 2009 to 2018). "Our results suggest that deletion of EPHA7 plays a role in the neurologic and dysmorphic features, including developmental delay, hypotonia, and ear malformations, observed in some 6q deletion patients." (PMID 19664229, 2009). "Phenotypic overlap between previously reported 6q16 deletion cases that have been characterized at the molecular level by array CGH with this case indicates that in humans EPHA7 plays a role in neurological and dysmorphic features such as developmental delay, hypotonia, and ear malformations." (PMID 19664229, 2009).
ovarian carcinoma (2 papers, 2017 to 2019). A malignant neoplasm originating from the surface ovarian epithelium. "Although having only 2 mutations within the FunFam boundaries of the gene EPHA7 itself, the MutFam (Ephrin type-B receptor 2) was found to be enriched based on 12 mutations found in Ovarian cancer across 8 genes within the FunFam." (PMID 30670742, 2019). "The expression of EPHA7, IFI16, SPP1 and TGFBI was confirmed at protein level in analyzed ovarian cancer patients.." (PMID 28611294, 2017). "Immunohistochemical analysis of selected (EPHA7, IFI-16, SPP1 and TGFBI) proteins was tested in ovarian cancer patients." (PMID 28611294, 2017).
Anxiety (1 paper, 2016). Intense feelings of nervousness, tension, or panic often arise in response to interpersonal stresses. "We therefore examined whether EphA7 knockdown within the dentate gyrus is sufficient to alter anxiety-related behaviors in the open field and elevated plus maze and in learning under stressful conditions in the two-way shuttle avoidance task." (PMID 27405707, 2016).
B-cell lymphomas (1 paper, 2008). "Promoter hypermethylation and silencing of EphA7 in mature B-cell lymphomas may serve to eliminate the inhibitory activity of secreted EphA7 on tumor-promoting EphA7 receptor signaling, thus enhancing tumor cell spread and recruitment of accessory cells able to promote tumor growth." (PMID 18366728, 2008).
benign prostate hyperplasia (1 paper, 2017). "To investigate whether the phosphorylation of EphA7 is correlated to ephrinA5 expression in clinical samples, we first used real-time PCR analysis to examine the mRNA level of EphA7 and its ligand ephrinA5 in 50 benign prostate hyperplasia (BPH) tissues and 64 PCa specimens." (PMID 29022918, 2017).
carcinoma of the maxillary sinus (1 paper, 2022). "Also miR‐204 sole as tumor suppressor that involved in pathogenesis of relative common carcinoma of the maxillary sinus by targeting EphA7 gene." (PMID 36381409, 2022).
cervical squamous cell carcinoma (1 paper, 2022). A squamous cell carcinoma arising from the cervical epithelium. "Furthermore, among cancers, the difference of EphA7 hypermethylation in cervical squamous cell carcinoma & endocervical adenocarcinoma (CESC) and normal tissues was the most prominent (△beta value = 0.464, P < 0.05); the median beta value was listed in Table." (PMID 35681118, 2022).
colon adenocarcinoma (1 paper, 2019). "Meanwhile, the TCGA database suggested that EPHA7 was downregulated in colon adenocarcinoma (COAD) tissues and rectum adenocarcinoma (READ) tissues, compared to the corresponding normal tissues." (PMID 31273190, 2019).
coronary artery disease (1 paper, 2011). "An example is two Ephrin receptors (EFNB2 Ephrin-B2 and EPHA7 EPH receptor A7) which Gentrepid predicted as candidates for coronary artery disease in the adjacent gene set." (PMID 22077927, 2011).
epilepsy (1 paper, 2017). A brain disorder characterized by episodes of abnormally increased neuronal discharge resulting in transient episodes of sensory or motor neurological dysfunction, or psychic dysfunction. "During the activation, various genes of our predicted EPH family have been identified to promote such biological processes, validating the crucial role of EPH family including our predicted genes EPHA3, EPHA4, EPHA5, EPHA7, and EPHB2 during epilepsy." (PMID 28255556, 2017).
Fibroadenoma (1 paper, 2011). A benign tumor of the breast characterized by the presence of stromal and epithelial elements. "A significantly higher percentage of human invasive ductal carcinoma samples displayed expression of EphA2, EphA4, or EphA7 in tumor epithelium relative to ‘normal’ samples (normal/hyperplastic or fibroadenoma), which were largely negative." (PMID 21935409, 2011).